LAG3 (lymphocyte activating 3)
Diseases named in the same sentence as LAG3 in open-access papers (continued):
Sharing a sentence is not in itself a finding about the gene and the disease.
tumor (continued). "Nevertheless, LAG-3 is currently considered a good target for immunotherapy in order to strengthen not only T-cell anti-tumor activity, but also the NK cell once probably through ADCC." (PMID 33255582, 2020). "Lag3 is another checkpoint receptor expressed by regulatory T cells and TILs that has been shown to dampen anti-tumor immune responses." (PMID 32429929, 2020). "In this regard, work in the MC38 murine tumor model has demonstrated that LAG‐3 synergizes with PD‐1 in the suppression of antitumor T cell responses and that dual blockade is often curative for established tumors resistant to either monotherapy." (PMID 32508018, 2020). "On the basis of preclinical or clinical evidence supporting its promising synergistic effects when combined with PD-1/PD-L1 blockade, inhibition of LAG3 will presumably play an increasingly important role in anti-tumor immunotherapy." (PMID 33488573, 2020). "The results were striking showing in both 4T1 and CT26 tumor models, that the combination of PI3Kδ-blockade and anti-LAG3 antibodies significantly improved control of tumor growth." (PMID 33093155, 2020). "MGD013 simultaneously targets LAG3 and PD-1, thereby blocking immune checkpoint inhibition, activating T cells, and enhancing anti-tumor immunity." (PMID 33488573, 2020). "Considering the function of LAG3 as an inhibitory checkpoint receptor known to be expressed on leukocytes, we assumed expression of LAG3 to correlate with levels of tumor infiltrating immune cells." (PMID 32861198, 2020). "Our results demonstrated that the expression of inhibitory receptors (including PD1, CTLA4, LAG3, and TIM3) were positively correlated and were associated with certain types of T cells in tumor tissues, especially CD8+ Tcm and CD8+ T cells." (PMID 32728493, 2020). "In profiling tumor-infiltrating lymphocytes, they found expression of PD-1, Tim3, and LAG3, which are checkpoint receptors." (PMID 33585560, 2020). "In multicolour immunofluorescence LAG3 positive cells within the tumour microenvironment were seen with co-expression of CD3, CD4 and CD8." (PMID 32592066, 2020). "LAG-3 is another checkpoint receptor that defines a potent regulatory T cell subset that occurs more frequently in cancer patients and is expanded at tumor sites." (PMID 33511078, 2020). "Galectin‐3 is a soluble galactoside‐binding lectin secreted by various tumor types that binds to LAG‐3 and suppresses antitumor CD8+ T cells." (PMID 32508018, 2020). "Elevated co-expression of LAG-3 and PD-L1 in tumor tissues from triple negative breast cancer (TNBC) patients treated with adjuvant therapy has been associated with poor disease prognosis." (PMID 32760400, 2020). "In summary, this study found that LAG‐3 was not only expressed in tumor‐infiltrating lymphocytes in NSCLC patients, it was also ectopically expressed in tumor cells, and this expression was associated with TNM staging." (PMID 32077528, 2020). "A phase I/II clinical study is evaluating anti-tumor efficacy and safety of anti-LAG-3 monoclonal antibody, BMS-986016 alone, or in combination with anti-PD-1 antibody (NCT01968109)." (PMID 33167514, 2020). "Paradoxically, some clinical reports indicated a favorable outcome of cancer patients when LAG-3 expression is observed on tumor-infiltrating immune cells." (PMID 33374804, 2020). "In the tumor microenvironment, LAG3 has a negative regulatory effect on T-cell responses, resulting in T-cell dysfunction." (PMID 33488573, 2020). "In tumor tissues, methylation correlated significantly with LAG3 mRNA expression, immune cell infiltrates (histopathologic lymphocyte score and RNA-Seq signatures of distinct immune infiltrates), and an interferon-γ signature." (PMID 32861198, 2020). "Nevertheless, other checkpoints are currently being studied for their potential roles in tumor immunity regulation such as lymphocyte activation gene-3 (LAG-3), T cell immunoglobulin-3 (TIM-3), and T cell immunoglobulin and ITIM domain (TIGIT)." (PMID 33042104, 2020).
tumor (continued). "LAG-3, TIM-3 and VISTA expression on immune cells was associated with an inflamed tumor microenvironment (CD8+ TILs) in the entire cohort (p < 0.001, p < 0.001, p = 0.007,) and in HPV-related OPSCC (p = 0.001, p < 0.001, p < 0.001)." (PMID 33396515, 2020). "This not only allowed us to identify correlates of successful tumor immunity, but conversely the key bottleneck preventing an effective immune response, and in particular, the crucial role of the inhibitory receptor LAG3 in controlling this balance." (PMID 33093155, 2020). "LAG-3 is expressed in TILs of several tumor types, such as breast, ovarian, and lung cancers, and its expression is related to the presence of PD-1+ T cells." (PMID 32751706, 2020). "Our study demonstrates a tumor cell-intrinsic mRNA expression of LAG3, which is regulated via DNA methylation." (PMID 32861198, 2020). "Knockout of the LAG-3 gene in a mouse model resulted in the inability of NK cells to kill certain tumor targets." (PMID 32117298, 2020). "In view of our results, we assume LAG3 methylation to be a crucial regulative mechanism of LAG3 expression and to be a sensible prognostic biomarker reflecting the complex molecular interplay within the tumor microenvironment." (PMID 32861198, 2020). "LAG3+ TILs have been identified in many tumor types, including lung, colon, breast, and pancreatic cancers and associated with aggressive clinical outcomes." (PMID 33519815, 2020). "On day 7, Isotype or Anti-Lag3 activated cells were adoptively transferred i.v. into the irradiated tumor-bearing mice." (PMID 32122464, 2020). "Still, both studies demonstrate that targeting LAG‐3 at various stages of an antitumor immune response does have the potential to improve tumor‐specific T cell reactivity." (PMID 32508018, 2020). "LAG3 is expressed on tumor-infiltrating lymphocytes (TILs), mediates T cell exhaustion and is subject to numerous currently recruiting clinical studies." (PMID 32232506, 2020). "LAG-3 is an established surface marker for NK-cell exhaustion and currently under investigation as a target for checkpoint inhibition in tumor immunotherapy." (PMID 33335526, 2020). "GL261 tumors showed the lowest frequency of KLRG1+ cells and CD25+ cells of the CD4 subset, whereas 70–80% of CD8 T cells in CT2A were positive for Lag3 and Tim3, markers of dysfunctional T cells in comparison to the other tumor types analyzed." (PMID 32764562, 2020). "Based on our results, we suggest the feasibility of LAG3 methylation to reflect anti-tumor response." (PMID 32861198, 2020). "For instance, previous studies reported that LAG-3 and PD-1 were co-expressed on tumor-infiltrating lymphocytes, and blockade of both pathways had synergistic effects on anti-tumor CD8+ T cell stimulation and response." (PMID 33329517, 2020). "Staining of TNBC specimens showed that TIL co-expression of FCRL6 and LAG3 was strongly correlated with elevated tumor-specific HLA-DR expression." (PMID 33162991, 2020). "Naive lymphocytes from LNs undergo activation and clonal expansion within the tumor, before PD1 and Lag3 expression, while tumor-associated myeloid cells promote the formation of a suppressive niche." (PMID 32433953, 2020). "A clear tendency towards a higher expression of GITR and LAG3 markers was also observed for tumor-infiltrating CD8+ T cells." (PMID 33126649, 2020). "Aim of the study was the evaluation and distribution of LAG3 on tumour infiltrating lymphocytes (TILs) and correlation with clinico-pathological and molecular data." (PMID 32592066, 2020). "Relatlimab is a monoclonal antibody against the lymphocyte activation gene-3 (LAG-3) on tumor infiltrating lymphocytes (TILs)." (PMID 32748171, 2020). "In tumor-bearing mice, LAG3 synergistically cooperated with PD-1 and contributed to tumor escape from immunosurveillance." (PMID 33584704, 2020).
tumor (continued). "The results showed that dual blockade of PD1 and LAG3 synergistically enhanced anti-tumor immunity by inhibiting tumor growth and enhanced infiltration of CD4+ and CD8+ T cells, combined with the increased production of IFN-γ and TNF-α." (PMID 33488573, 2020). "In our analysis of the tumor-infiltrating immune cells, higher proportions of PD-1+ LAG3+ CD8+ T cells were present in the tumors of control mice." (PMID 33247183, 2020). "To avoid the potential bias generated by tumor stage we validated the predictive significance of LAG3 methylation in the ICB cohort, which is exclusively composed of stage IV patients." (PMID 32861198, 2020). "The triple-downregulation of PD-1, TIM-3, and LAG-3 in anti-Her2 CAR T cells using short hairpin RNA cluster resulted in enhanced tumor control in mice." (PMID 32455836, 2020). "LAG3 positive tumours with tumour stages > pT2 had a median OS of 70.2 months (95% CI 20.6–32.0 months), while LAG3 negative tumours with tumour stages > pT2 showed a median OS of 25.0 months (95% CI 2.1–154.6 months) (p = 0.037)." (PMID 32592066, 2020). "Once the T lymphocytes during tumor progression have been exhausted, this phenomenon is accompanied by the increment of inhibitory receptors for LAG-3." (PMID 33114418, 2020). "The expression and upregulation of LAG-3 and PD-1 on tumor-infiltrating lymphocytes (TILs) leading to the inactivate of effector T cells and cause tumor growth." (PMID 32195194, 2020). "A tumor-specific increase in Lag3 expression compared to LNs was also detected at the protein level." (PMID 32433953, 2020). "Specifically, we evaluated the interactions of LAG-3 and its ligands between T cells and tumor cells." (PMID 32686767, 2020). "To verify that FABP5highCD8+ T cells are exhausted, we tested the expression of additional exhaustion markers (TIM3, CTLA4, and LAG3) in cells from tumor sample by flow cytometry." (PMID 32611686, 2020). "Again, the most frequent immune targets in CD4+ T cells from patients with GBM, in descending order, isolated from the tumor microenvironment were A2aR > PD-1 > CTLA-4 > CD39 > TIGIT > FOXP3 > LAG-3 > CD160 > TIM3 > KIR > CD73." (PMID 32721947, 2020). "Gal-3 binds activated-committed CD8 T cells only in the tumor microenvironment and suppresses their anti-tumor response via Lymphocyte-activation gene (LAG)-3 and by inhibiting the expansion of plasmacytoid dendritic cells." (PMID 32695112, 2020). "In terms of CD8+ T lymphocytes and NK cells, LAG-3 does not work through MHC-II but rather works through LSECtin, another ligand of LAG-3, which is mainly expressed on tumor cells." (PMID 32944390, 2020). "In particular, IL6 released by tumor cells played a major role in promoting LAG3+ cell polarization." (PMID 33327433, 2020). "Whereas the role of LAG3 protein expression in immune cells, particularly within the orchestra of tumor microenvironment, has been studied in detail, the role of LAG3 in cancer cells is not well understood." (PMID 32861198, 2020). "LAG-3, PD-1 and other inhibitory receptors are often co-expressed on tumor-infiltrating T cells in various types of cancers, such as squamous cell carcinoma, NSCLC, ovarian cancer, melanoma, colorectal adenocarcinoma, and fibrosarcoma." (PMID 32714324, 2020). "In addition to TIM-3, expression of another immune suppressive receptor, lymphocyte activation gene-3 (LAG-3), is also increased in immune infiltrates of HCC tissues, suggesting that PD-1, TIM-3, and LAG-3 may cooperate and are implicated in inducing anti-tumor immune tolerance." (PMID 32443599, 2020). "Analysis of LAG3 mRNA expression in different tumor tissue sites showed higher expression of LAG3 mRNA in regional lymph nodes and cutaneous metastases compared to primary tumors and distant metastases." (PMID 32861198, 2020). "Lee et al38 investigated that PD‐L1, LAG3 and IDO1 expressions in tumour‐infiltrating immune cells were significantly associated with a better disease‐free survival." (PMID 32227579, 2020).
tumor (continued). "Here, LAG3 mRNA expression and methylation patterns were opposed to the pattern observed in the TILs: Purity of tumor tissue and tumor cell content (% nuclei that are tumor cells) showed significant inverse correlations with LAG3 mRNA expression." (PMID 32861198, 2020). "This complex ecosystem of tumor and immune cells provides new insights into UM biology, and LAG3 is identified as a potential candidate for immune checkpoint blockade in patients with high risk UM." (PMID 31980621, 2020). "On the other hand, the expression of inhibitory molecules such as CTLA4, PD-1, and LAG3 on CD8+ T cells are promoted by IL-6 and IL-10, that produced by tumor cells and tumor-associated macrophages, in turn inhibit CD8+ T cells infiltration." (PMID 32208363, 2020). "These authors found that dual PD-1/LAG-3 blockade in Eμ-TCL1 mice effectively reduced tumor load and restored an antitumor immune response." (PMID 33329575, 2020). "Our results are in accordance with data of several tumor models which demonstrated Tregs to express LAG3 in dynamic levels, depending on the state of activation." (PMID 32861198, 2020). "It suggests that IDO1, PD‐L1 and LAG3 were partially regulated by the same mechanism or inducer in tumour." (PMID 32227579, 2020). "As one of the key checkpoint receptors for both T and NK cells, LAG-3 is becoming a major target for blockade to restore the anti-tumor capacity in the therapy of various types of cancer." (PMID 32714324, 2020). "The median OS was 70.2 months (95% confidence interval (CI) 1.9–138.5 months) in LAG3 positive tumours compared to a median OS of 26.9 months (95% CI 21.9–31.8 months, p = 0.046) in LAG3 negative cases." (PMID 32592066, 2020). "The expression of PD-1, TIM-3 and LAG-3 on tumor infiltrating lymphocytes is also increased in SMA-560 tumors." (PMID 33374542, 2020). "A co-expression of LAG3 and PD-L1 on tumor-infiltrating lymphocytes (TILs) has been observed in several tumor types." (PMID 32232506, 2020). "Other mouse studies revealed that anti-LAG-3 mAbs enhanced anti-PD-1 therapies and increased the secretion of activating cytokines released by tumor-infiltrating T cells." (PMID 33304346, 2020). "LAG-3 blockade has also been shown to synergize with antitumor vaccination to improve tumor-specific CD8+ T cell activation." (PMID 32944390, 2020). "In a large set of 421 patients with EAC, we report the impact of the checkpoint inhibitor LAG3 considering the protein and mRNA expression, as well as the distribution pattern within the tumour, in correlation with clinical and molecular data." (PMID 32592066, 2020). "Previous preclinical studies have reported that overexpression of lymphocyte activation gene-3 (LAG-3) as the coinhibitory molecules on CD8+ T cells can regulate T-cell tolerance to tumor antigens." (PMID 33062666, 2020). "The increased Lag3 expression was detected in T cells from CLL tumor microenvironment, and blocking Lag3 improved T cell activation." (PMID 33150182, 2020). "Tr1 cells co-express the surface markers CD49b and Lag-3 and are upregulated in peripheral blood and in the tumor microenvironment in glioblastoma patients." (PMID 32117316, 2020). "Although the impacts of LAG-3-MHC-II interaction on CD4+ T cell immunity have been well studied, it was poorly understood as to how LAG-3 negatively regulates CD8+ T cell-mediated anti-tumor immunity." (PMID 32787882, 2020). "The multi-spot TMA demonstrated a heterogenic LAG3 distribution within the eight tumour spots; however, by comparing the tumour surface with the infiltration margin, we found a consistent expression pattern of LAG3." (PMID 32592066, 2020). "As most data on NK-cell exhaustion was generated in the context of anti-tumor immunity, little is known about LAG-3+ NK cells in healthy donors." (PMID 33335526, 2020).
tumor (continued). "Recently, the fibrinogen like protein 1 (FGL-1) that is naturally expressed by liver cells and overexpressed by some tumor cells, was also characterized as a new ligand for LAG-3 which can potently prevent T cell activation upon binding." (PMID 33519801, 2020). "LAG3 is expressed both on Treg cells and exhausted TILs in the tumor microenvironment, suggesting a role in tumor immune evasion and that blockade can restore T cell anti-tumor function." (PMID 30621125, 2019). "Coexpression of PD‐1 and LAG‐3 has been suggested to identify dysfunctional tumor‐infiltrating lymphocytes in NSCLC." (PMID 31273938, 2019). "Soluble LAG-3 promotes cellular maturation and migration, resulting in further improvement of anti-tumor immunity against these antigens." (PMID 30788290, 2019). "Analysis of the expression of co-inhibitory markers (PD-1, TIM-3 and LAG-3), which has been described for exhausted virus- and tumor-secific T cells, was less conclusive after proliferation in PSPA." (PMID 31568490, 2019). "In solid tumors, LAG3 is upregulated on tumor-infiltrating lymphocytes (TILs), while blockade of LAG3 can enhance anti-tumor T cell responses." (PMID 31623599, 2019). "The co-blockade of TIM-3 and PD-L1 or LAG-3 and PD-1 enhanced the therapeutic efficacy, and increased the ratio of cytotoxic T cells: Tregs in the tumor compared to targeting PD-L1 or PD-1 alone." (PMID 31614877, 2019). "Both PD-1 and LAG-3 were positive on tumor cells in only a minority of DLBCL samples (8.3% and 7.5%, respectively)." (PMID 31007846, 2019). "In the in vitro studies, we demonstrated blocking activity by anti-TIM-3 and anti-LAG-3 compounds in our experimental model system consisting of tumor-primed cytotoxic CD8+ T cells." (PMID 31007846, 2019). "These inhibitory receptor-ligand interactions appear to promote increased tumor growth and immune evasion by increasing PD-1 and Lag-3 expression by tumor infiltrating T cells." (PMID 31244852, 2019). "Preclinical research demonstrated that monoclonal antibody (mAb) mediated LAG-3 blockade activates antigen-specific T cells at the tumor site, ultimately leading to a disruption in tumor growth." (PMID 31569553, 2019). "Lag3 and PD-1 are co-expressed on functionally impaired (“exhausted”) tumor-infiltrating lymphocytes (TILs), thereby contributing to tumor-mediated immune suppression both in preclinical models and in cancer patients." (PMID 31695037, 2019). "Following the accomplishments of PD-1 and CTLA-4 blockade, TIM-3 and LAG-3 are currently being explored in various pre-clinical and clinical trials to promote effective anti-tumor immunity for clinical benefits." (PMID 31921188, 2019). "Because LAG-3 engages with DCs, it is possible that LAG-3 blockade can promote innate immunity, a first host defense mechanism, hence stopping tumor growth at an early stage." (PMID 30941125, 2019). "In a study involving 135 primary ccRCC cases and 51 metastatic ccRCC cases, PD-L2 expression in tumor cells and LAG3 expression in TILs were identified as poor prognostic factors in ccRCC patients." (PMID 31783776, 2019). "Through their research on cancer, these researchers found that FGL1 is the main ligand of the immunosuppressive receptor LAG-3 and participates in the immune escape mechanism of tumor cells." (PMID 31921022, 2019). "In syngeneic mouse tumor models of fibrosarcoma or adenocarcinoma, a combination of anti-PD-1 and anti-LAG-3 antibodies had a synergistic effect on tumor growth inhibition." (PMID 31007846, 2019). "A panel of anti-LAG-3 Nbs was investigated using various techniques in order to identify the most optimal targeting moiety for the molecular imaging of LAG-3 expression in the tumor microenvironment." (PMID 31569553, 2019). "We determined the immunohistochemical expression of PD-1, PD-L1, TIM-3, and LAG-3 on tumor cells and on tumor infiltrating lymphocytes (TILs) among 123 DLBCL patients." (PMID 31007846, 2019).